TGFB1 (transforming growth factor beta 1)
Diseases named in the same sentence as TGFB1 in open-access papers (continued):
Sharing a sentence is not in itself a finding about the gene and the disease.
tumor (continued). "KLF4 is a Yamanaka factor important for pluripotency, while SMAD3 is essential for TGFB1 signaling, and PPARG has complex roles in tumor metabolism and immunity; they have known roles as positive and negative regulators of EMT and bladder carcinogenesis." (PMID 38129585, 2023). "One study used commercial GBM cell lines to show that CCL21-CCR7 induced tumor cell invasiveness and epithelial-mesenchymal transition (EMT) in a TGFβ1 dependent manner in vitro." (PMID 37314567, 2023). "Looking at these results, it can be said that the decreased VEGFA, E-cadherin, TGFβ1 and EGFR expression in PD-L1 low tumor cells after treatment is specific to anti-PD-L1 MoAb treatment." (PMID 38152616, 2023). "In Treg cells, TCF1 deletion has been shown to upregulate Foxp3, IL2Ra (CD25), and TGFβ1, as well as other activation markers, and are superior at suppressing CD8 T cell proliferation and tumor control." (PMID 37552475, 2023). "TGFB1 belongs to the TGF-β family and is a common immunosuppressive medium that promotes tumor progression." (PMID 37318594, 2023). "The mo-Macs were predicted to deliver activation signals through the TNFR (TNF-TNFRSF1A), TGFBR (TGFB1-TGFBR2), and EGFR (EREG-EGFR) pathways to tumor cells." (PMID 37187731, 2023). "Mechanically, tumor cells educated neutrophils via TGFβ1 to produce more FAM3C through Smad2/3 signaling activation, and FAM3C promoted tumor cell EMT through JNK-ZEB1/Snail signaling pathway." (PMID 37056931, 2023). "In MDS and CML, TGFB1 expression was positively correlated with tumor-suppressive components like NK and T cells but was negatively correlated with EMT and tumor proliferation rate." (PMID 37925591, 2023). "They discovered that tumor cells can stimulate CAF activation by upregulation of α-smooth muscle actin and production of transforming growth factor-β1 (TGFβ1)." (PMID 37746966, 2023). "These analyses also showed that expression of VIM, TGFβ1, α-SMA, CD44 and CD133 had significantly high expression in metastatic compared to primary tumours." (PMID 37174052, 2023). "Tumor cells can secrete IL10, CXCL8, and TGFB1, which directly reduce NK cell cytotoxic functions and/or recruit other immune cells such as Treg cells, MDSCs, CD11b + Ly6G + neutrophils, and DC, thus inhibiting NK cell functions indirectly." (PMID 37190251, 2023). "The decrease of VEGFA, TGFβ1 and EGFR upon anti-PD-L1 treatment in PD-L1 low tumor cells provides a rationale for the use of those antibodies in PD-L1 low tumors." (PMID 38152616, 2023). "In tumor tissue from BC patients, NF-kB, STAT3 and their target genes (i.e., cyclin-D1, VEGF-A, and TGFβ1) have been found to be activated in comparison to healthy tissue, suggesting that chronic inflammation can promote tumor development." (PMID 36614308, 2023). "Overexpression of the cytokine transforming growth factor β1 (TGFβ1), a potent inducer of EMT, is frequently detected in the tumor microenvironment and correlates with invasion and lymph metastasis." (PMID 38055067, 2023). "Low passage tumor alone secreted high concentrations of CCL2/MCP1, CXCL8/IL-8, CXCL1/GRO, IL-6, CXCL10/IP10, G-CSF, TGFβ1, MMP1, CCL3/MIPα, GM-CSF and EGF." (PMID 37063842, 2023). "TGFβ (TGFB1) in the TME inhibits immune activity against tumors and promotes tumor growth and survival." (PMID 37760450, 2023). "Our results showed that tumor targeting-related immune checkpoint genes such as CD274 (p = 0.0137), TGFB1 (p = 0.0175), PDCD1 (p < 0.001), CTLA4 (p < 0.001), and LAG3 (p < 0.001) were significantly associated with APOC1." (PMID 36969562, 2023). "This hypoxia-induced glycolysis promotes lactate secretion, enhancing the activation of TGFβ1/p38 mitogen-activated protein kinase/matrix metalloproteinase 2/9 (MAPK/MMP2/9) signaling in breast cancer cells, promoting the invasiveness of tumor cells." (PMID 37168385, 2023). "The IHC expression of TGFβ1 in primary and metastatic RCC tumours and adjacent normal tissue was evaluated by IHC." (PMID 37174052, 2023).
tumor (continued). "In conclusion, our study demonstrates that tumor cells educate TANs via TGFβ1 to produce more FAM3C, which mediates tumor cell EMT." (PMID 37056931, 2023). "To determine the molecular signals between polarized TAM and PrC cells, we focused on TGFβ1, which is a highly secreted factor by M2/TAM cells to exert a strong effect on tumor cell growth." (PMID 35967419, 2022). "Transforming growth factor beta 1 (TGF-β1), secreted by stromal and tumor cells, enhances the transition of fibroblasts into CAF, resulting in tumor migration and metastasis." (PMID 36616017, 2022). "We selected TGFβ1 for EMT induction, as this is a naturally abundant cytokine in tissues secreted by immune and other cells which populate the tumour microenvironment." (PMID 36101425, 2022). "The results showed that the growth factor LR interacts with PDGFB : PDGFRA, IGFBP4:FZD8, and TGFB1:SDC2 with TAMs and tumor vascular cells." (PMID 35664733, 2022). "They involve STAT3-inducing cytokines (IL-10, IL-6 and LIF), TGFB1 mainly expressed by TAMs, WNT7A mainly expressed by tumor cells, multiple S100 genes, semaphorins and their receptors (plexins and neuropilins), ephrins, chemokines and their receptors." (PMID 35682890, 2022). "TGFB1, TGFB3, NOG, and SMAD9, components of the TGF-β pathway, participate in tumor metastasis and cancer stem cells." (PMID 36344487, 2022). "One of the functions of TGFβ-1 is to induce EMT, which is important biological process critical during embryogenesis, but it is also exploited by cancer cells during tumor progression." (PMID 35931724, 2022). "As expected, ITGA5, PLAU, PLAUR, SERPINE1, TGFB1, and VEGFC were consistently overexpressed in tumor tissues compared to normal tissues (log2FC > |1| and p ≤ 0.01)." (PMID 36425786, 2022). "Usually, activated cytotoxic T lymphocytes (CTLs) can attack cancer cells to suppress tumor growth, while TAMs express immunosuppressive cytokines, chemokines, and growth factors like IL10 and TGFB1 to make CTLs hyporesponsive." (PMID 36211379, 2022). "TGFB1, IL-6 and CXCL12 played an important role in the cell-cell communication between residual tumor cells and CAFs." (PMID 35784460, 2022). "Transcription of ESR1 gene is subjected to inhibitory autoregulation that was predicted to involve a network consisting of a multifunctional tumour suppressor gene DIRAS3, TGFB1, and transferrin receptor TFRC." (PMID 35218417, 2022). "The gene expression of IL-10, TGFb1, S100A8, S100A9, and IL10RA was increased in TAMs compared to tumor cells isolated from ascites of OC patients." (PMID 35682890, 2022). "An inflammatory tumor microenvironment facilitates EMT, i.e., through the upregulation of transforming growth factor-beta 1 (TGF-β1) and its receptor signaling." (PMID 36077778, 2022). "While TGFB1 is homogeneously expressed, INHBA expression is restricted to highly infiltrative tumor tips." (PMID 35986012, 2022). "Further, studies have reported that tumor exosomes express NKG2D ligands together with other molecules, including TGFβ-1, which trigger the downregulation of the NKG2D receptor expression." (PMID 36741391, 2022). "The significant correlation between DDR1 and regulatory T cells and T-cell exhaustion markers such as TGFβ1, PD-1, and CTLA-4 indicated that DDR1 was involved in immune escape and tumor invasion." (PMID 35935941, 2022). "In this study, genes including THBS1, CDKN1A, FBN1, TGFB1, and IGFBP3 were found to be downregulated in tumor cell lines." (PMID 35340229, 2022). "Among them, TGFB1 and VEGFA are tumor-secreted immunosuppressive factors, while CD274 (PDL1) and PDCD1LG2 are both PD1 ligands and cell-surface immunosuppressive factors." (PMID 35222383, 2022). "This has been shown to translate into limited control of primary tumor growth and metastatic dissemination in models of NSCLC and PDAC, through a mechanism that relies on STAT3 signaling in TREG cells and TGFB1 secretion." (PMID 36319998, 2022).
tumor (continued). "The transforming growth factor beta-1 (TGF β-1) cytokine exerts both pro-tumor and anti-tumor effects in carcinogenesis." (PMID 35858839, 2022). "A previous study indicated cytokine TGFβ promoted tumour immune evasion and resistance to ICB therapy, and the elevated expression level of TGFB1 in our EIC also verified the potential resistance of the EIC patients." (PMID 35799269, 2022). "Particularly, the upregulated expression of TGFB1 increases the secretion of TGF-β, a significant cytokine mediating immunosuppression of tumor cells." (PMID 36003368, 2022). "Metabolic imbalances in the skeletal muscle are mediated by tumour-derived pro-inflammatory cytokines, such as tumour necrosis factor-α (TNF-α), interleukin-1 (IL-1), IL-6, and transforming growth factor β1 (TGFβ1)." (PMID 35406121, 2022). "Through immune checkpoint gene expression analysis, the expression of HM13 was found to exhibit a significant correlation with several tumor inhibitory genes, especially VEGFB, LAG3, CD274, and TGFB1." (PMID 36046831, 2022). "In detail, tumor cells upregulated COL20A1, COL28A1 and TGFB1 expression to recruit more myofibroblasts in TTs compared with in PTs." (PMID 35361264, 2022). "A positive correlation of the Hypoxia_DEGs_Score with the expression of TGFB1 and TGFB2 suggests that the hypoxic status of HCC results in a tumor immunosuppressive state with increased infiltration of immunosuppressive cells." (PMID 36059442, 2022). "Of these genes, ITGA5, PLAU, PLAUR, SERPINE1, TGFB1, and VEGFC were significantly highly expressed in tumor compared to normal tissues." (PMID 36425786, 2022). "Conversely, FAT-WT patients had suppressive TME with high expression of CCL2, CXCL12, CXCL14, CD40, ENTPD1, TGFB1, and VEGF; these factors have been confirmed to promote angiogenesis, invasion, and metastasis of tumor cells." (PMID 35836939, 2022). "In this study, we discovered that PDK1 and PDK2 are metabolic checkpoints for tumor progression and CSC features under TGFβ1 modulation within the TME of HNC." (PMID 36474273, 2022). "RN7SL1 restricts myeloid-derived suppressor cell development, decreases transforming growth factor beta 1 (TGFB) in myeloid cells, and fosters dendritic cell subsets, which led to the endogenous expansion of effector-memory and tumor-specific T cells." (PMID 36338771, 2022). "This remarkable therapeutic effect is believed to be largely related to TGFB1 which leads to highly selective and focused amplification of MSCs‐based NIS expression in the tumor environment." (PMID 34981659, 2022). "Integrin αvβ3 mediates EMT induction by several factors, such as transforming growth factor-beta 1 (TGF-β1), pituitary tumor transforming gene (PTTG), and fibroblast growth factor 1 (FGF1)." (PMID 35682554, 2022). "Analysis of the five hypoxia- and immune-related genes also showed high expression of EPO, TGFB1, TGFA, and PLAUR, but low expression of TEK in tumor samples." (PMID 35222525, 2022). "More importantly, FOLR2+ TAMs significantly expressed typical immunosuppressive genes including TGFB1, TGBR1, IL10, and IL10RB, validating the immunosuppressive role of FOLR2+ TAMs in the HCC tumor niche." (PMID 36238304, 2022). "Moreover, in in vivo preclinical tumor models, anti-PD-1 therapy can exacerbate high TGFβ signaling through activation of another checkpoint on exuberant T cell activation, the secretion of TGFβ1 from activated CD4+ T helper type 1 (Th1) cells, as well as other mechanisms." (PMID 36382146, 2022). "In particular, TEV released from tumour-educated platelets stimulate MAPK p42/44 and AKT, increase the expression of MMP1, MMP9, VEGF and cyclin D2 and induce EMT by activating TGFβ1 and NF-κB signalling." (PMID 36011012, 2022). "In this case, the isolated CAF-derived EVs carried elevated levels of TGFβ1, which promoted activation of the SMAD signaling pathway in these tumor cells." (PMID 33540535, 2021).
tumor (continued). "Here, TGFβ1 upregulates PDGFRβ expression in peritumoral CD90+CD73+ cells, which is invovled in the recruitment of pericytes to growing tumours via tumor-derived PDGF-BB." (PMID 34740105, 2021). "Transforming growth factor-beta 1(TGF-β1) and BMP-2 are members of the transforming growth factor-beta family, which exert important roles in tumor growth and invasion." (PMID 34221185, 2021). "Several marker genes, FOXP3, STAT3, PDCD1, TGFB1, IL10, HMGB1, which are significantly related to the tumor microenvironment induced by radiation, had significant functional differences in the distribution of CD8+T cells clusters." (PMID 33968889, 2021). "To further affirm the connection between TGFβ1 and the immune microenvironment, we applied CIBERSORT algorithm to examine the ratio of tumor-infiltrating immune cells in CC." (PMID 33995472, 2021). "In conclusion, the overexpression of LAMC1, upregulated by TGFβ1 via SMAD4/SP1 synergistic activation, promoted the proliferation and migration of tumor cells mainly via NF‐κB/MMP9‐MMP14." (PMID 34218518, 2021). "Higher serotonin levels, tgfβ1 production, and HSC numbers were also observed in xmrk and Myc male tumours." (PMID 34680297, 2021). "FN1, ITGA5, THBS2, and LAMA1 were associated with cell adhesion and metastasis, and the expression of TGFB1, COL4A1, COL4A2, and THBS2 inhibited tumor growth." (PMID 34370778, 2021). "In fact, TGFβ1 and soluble ligands for NKG2D have been detected in cancer cell lines and in tumor cells isolated from mesothelioma pleural effusions." (PMID 33671415, 2021). "After normalization of mRNA expression values of TGFβ1 and FoxP3 of HCC tumors to the values of matched peritumor tissues, we found an inverse correlation between the net tumor expression of these markers." (PMID 34769191, 2021). "Noticeably, TGFβ1 activation promoted HCC metastasis, as indicated by higher tumor incidence in the liver, abdominal lymph nodes as well as other organs." (PMID 33608500, 2021). "Here, TGFβ1 increased FAP expression in CD90+CD73+ peritumoral cells and FAP+ cells were observed adjacent to and surrounding tumour epithelium." (PMID 34740105, 2021). "TGFβ1 triggers Raf/MEK/ERK and PI3K/AKT signaling pathways to promote tumor malignancy in some types of cancers." (PMID 34249724, 2021). "In these immunosuppressive marker genes, PD-L1, TGFB1, and IL10 were significantly correlated with FUCA2 expression in most tumor types." (PMID 34745134, 2021). "Notably TGFβ1 and receptors for TGFβ are known cargos of exosomes and it is thus highly likely, that either TGFβ itself or components of the TGFβ signaling machinery may be delivered to tumor cells to impact EMT." (PMID 33590419, 2021). "We found that CXCL14, TGFβ1, and TNFSF10 were highly expressed in tumor tissues compared with adjacent normal samples." (PMID 34167551, 2021). "Each CD44+ cell-type functions immunosuppression through different ways: CD44+ tumor cells express CD276, IL13, VEGFA, and IDO1; CD44+ TAMs express IL10, TGFB1, VEGFA, and HAVCR2; CD44+ T cells express CD274, TGFB1, CTLA4, LAG3, and PDCD1." (PMID 35187044, 2021). "One of the key steps in the metastatic process is cancer cell EMT and CAFs have been described to secrete growth factors such as transforming growth factor beta 1 (TGFβ1), EGF, PDGF and HGF that will promote EMT in primary tumor cells." (PMID 34201840, 2021). "TGFB1 is a key modulator of angiogenesis, by regulating cell proliferation and migration, as well as regulation of ECM turnover and suppression of anti-tumor immunity." (PMID 34771552, 2021). "H19 can act as a competing endogenous RNA of miR-370-3p, resulting in the promotion of TGFB1-induced EMT, and as an inhibitor of a tumor-suppressor miRNA let-7, resulting in increased tumor cell migration and invasion." (PMID 34680193, 2021). "In these immunosuppressive marker genes, TGFB1, NECTIN2, LGALS9, LAG3, and IL10RB were significantly correlated with CCDC137 expression in most tumor types." (PMID 34055889, 2021).
tumor (continued). "Second, previous studies revealed that PRDX1 excessive expression enhances epithelial-mesenchymal transition (EMT) by inducing transforming growth factor beta 1; EMT is regarded as a critical process in tumor invasion and metastasis." (PMID 33747258, 2021). "TGFβ1 is a crucial regulator of epithelial-mesenchymal transition (EMT), a key process in tumor metastasis." (PMID 34096887, 2021). "We found the positive correlation between HILPDA expression and immunosuppressive genes, such as PD-L1, PD-1, TGFB1, and TGFBR1, indicates the key role of HILPDA in regulating tumor immunosuppressive microenvironment." (PMID 33816230, 2021). "We further show that in primary resected NSCLC tumours, peritumoral cells that coexpress CD90 and CD73 are enriched in genes comprising the ECM/stromal gene signature, which were enhanced by TGFβ1." (PMID 34740105, 2021). "TGFβ1 and the receptor subtype-2(TGFβrII) have been identified in SI-NEN samples, confirming the interaction of tumor cell with TME to exert its pro-fibrotic role in NENs." (PMID 32521677, 2020). "We found that these receptors are highly correlated to the innate and adaptive immunity-related cells, as well as IL-10, IL-6, CXCL10, CCL2-CCL5, TGFB1 in KIRC tumors, whereas in KIPRP tumor tissues IL8, IL1A, and TNF were highly correlated." (PMID 33330620, 2020). "RAC1, via PAK1, drives TGFβ1-induced prostate cancer cell EMT, as well as EMT and tumor growth in gastric cancer." (PMID 33266416, 2020). "At the advanced stages of cancer development, TGFβ1 can accelerate cell proliferation, induce EMT, and enhance the invasion and migration of stem-like cancer cells, resulting in tumor metastasis." (PMID 33023180, 2020). "Beside TGFβ1, CAF secrete strong mitogenic factors for HCC cells, such as hepatocyte growth factor (HGF) and epiregulin that promote tumor growth." (PMID 32899119, 2020). "AUC of the existed tumor markers including AFP, GPC-3 and TGFβ1 were 0.679, 0.879 and 0.577, respectively." (PMID 33282554, 2020). "Therefore, therapeutically increasing RAC1B expression in poorly differentiated cancer cells from PDAC or TNBC may be a promising strategy to block the tumor-promoting functions of TGFβ1 and eventually enhance their redifferentiation to the less malignant epithelial phenotype." (PMID 32545415, 2020). "First, we showed here that low expression of HSD17B6 led to high expression of TGFB1 through DHT, and then promoted tumor development in HCC." (PMID 32514254, 2020). "The tumor volumes, weight and microvessel density (MVD) in the HCT-15/FU group were distinctly higher than those in the HCT-15 group, and the addition of TGFβ1 counteracted this tendency." (PMID 33193874, 2020). "Measurements of 36 different chemokines in the culture medium revealed a significant decrease in the secretion of CCL5, CCL8, CXCL1, CXCL2, CXCL5, and TGFβ1 and a significant increase in TGFβ2 secretion by TB9-Fhit transfected tumor cells." (PMID 32545680, 2020). "Combined therapy suppressed tumor growth and modulated TME, decreasing IL-17 and TGFβ1 while reducing infiltrated MDSCs and reversing CD8+ T cell suppression." (PMID 33335860, 2020). "Surprisingly, when interacting with apoptotic cancer cells in conditioned medium, TAMs inhibits TGFβ1-induced EMT and thus tumor invasion, which is considered the antitumor role of TAMs." (PMID 32264958, 2020). "Our results identify strong contributions of epithelial-to-mesenchymal transition (EMT), classical tumor-promoting (such as E2F, KRAS, MYC, mTORC1, and TGFB1 signaling) and immune-related pathways in the tumor epithelium of COSCC." (PMID 33142242, 2020). "TGFβ1/TβRs stimulates the SMAD2/3 signaling pathway, which is involved in physiological development, host immunity, inflammation and in tumor progression, and invasion." (PMID 32766254, 2020).